MMP9 (matrix metallopeptidase 9)
Diseases named in the same sentence as MMP9 in open-access papers (continued):
Sharing a sentence is not in itself a finding about the gene and the disease.
tumor (continued). "They contain MMP-9, which triggers the release of vascular endothelial growth factor (VEGF) in pancreatic and lung cancer patients by degrading the extracellular matrix, thereby promoting tumor growth." (PMID 39143953, 2024). "The expression and activity of MMP9 are regulated by various tumor-related factors, including TGF-β, EGF, and FGF, which participate in the regulation of multiple signaling pathways involved in tumor initiation and progression." (PMID 38769413, 2024). "The inhibitory effects of HSYA on tumor angiogenesis were further demonstrated by decreasing the expression of MMP-9 and bFGF, as well as MMP-9 mRNA, regulating the degradation of the blood vessel basilar membrane, blood vessel migration, and tumor vascularization in BGC-823 cells." (PMID 38611849, 2024). "These in vivo results were well in agreement with the in vitro experiments, providing strong evidence that the HIL@Z/P/H+Red+NIR treatment maybe alleviate tumor hypoxia to inhibit lung metastasis by downregulating the levels of HIF-1α and MMP-9." (PMID 38280861, 2024). "In contrast, they may also support angiogenesis and MMP9 degradation in the ECM and promote metastasis by releasing VEGF, which is beneficial for tumor progression." (PMID 38840910, 2024). "Furthermore, signal transduction pathways like PI3K/AKT play a significant role in MMP9 regulation in CRC, influencing tumor cell proliferation, survival, and invasion." (PMID 39664453, 2024). "Thus, we also analyzed the mRNA expression of MMP1, MMP9 and FMOD in MACS-separated tumor cells that has been cocultured with tumor-matched and unmatched CAFs or NOFs for seven days." (PMID 38822309, 2024). "Consequently, the decreased expression of ZFP36L2 leads to the increased secretion of cytokines, such as IL1β, MMP-9, and TNF-α, by T cells, thereby promoting tumor apoptosis." (PMID 39767767, 2024). "CPT-TMC plays a significant role in anti-lymphatic production and anti-angiogenesis, lowering the expression of VEGF-D and MMP-9, reducing LMVD, MVD and KI-67 positive cells, increasing the tumor apoptosis index, and reducing the systemic side effects caused by CPT." (PMID 39464892, 2024). "In addition to the importance of markers associated with immune cells in the primary tumor to predict the BCLM TME, the relevance of primary tumor cell–ECM interactions, including E-cad, MMP9, and αSMA, was evident by their rankings for ML classification." (PMID 39373616, 2024). "In contrast to other macrophages, TAMs have specific receptors and ligands; for example, TAM can enhance phagocytosis by binding to extracellular matrix metalloproteinase ligands (e.g., MMP-2, MMP-7, MMP-9, and MMP-12), which in turn promotes tumor growth and metastasis." (PMID 38806553, 2024). "Additionally, tumor tissue analysis revealed a significant decrease in ICAM1, MMP9 and MUC1 expression following atorvastatin treatment, along with inhibited MAPK pathway activation." (PMID 38907234, 2024). "Furthermore, the overall abundances of IL-8 and MMP-9 were low, with a higher prevalence of expression observed in both TAM and tumor cells." (PMID 39574472, 2024). "Moreover, MMP9’s responsiveness to oxidative stress through ROS interaction and its regulation via PAR2 activation add layers to its role in modulating the tumor microenvironment and promoting invasiveness." (PMID 39664453, 2024). "used a PLGMWSR‐OH linker to design CXCR4‐targeted iron oxide nanoparticles (IONPs) which could be activated by MMP‐9 and self‐assembled to give a T2 signal enhancement by about 160% in U87.CD4.CXCR4 tumor." (PMID 39175888, 2024). "Multiple MET markers (CitH3, MPO, MMP2, MMP9, and MMP12) were elevated in macrophages that were co-cultured with tumour cells, but this effect could be rescued by treatment with MET inhibitor (Cl-amidine, a specific PADI4 inhibitor) or GW." (PMID 39025845, 2024). "The MMP-9 and TGF-β are M2 macrophage markers and play roles in tumor progression." (PMID 38589471, 2024).
tumor (continued). "The presented results indicate the significant correlation between the CXCL12, CXCR4, CXCL8/CXCR2, M-CSF, MMP-2, MMP-9 ADAM17, ADAMTS-6, and CLDN7 levels and tumor stage, as well as the clinicopathological parameters of OC, such as the presence of lymph node and/or distant metastases." (PMID 38673838, 2024). "MMP9 turns on the “angiogenesis switch” by inducing the release of vascular endothelial growth factor (VEGF) in the ECM, resulting in expanded vascularization and tumor growth." (PMID 39061147, 2024). "Rich granules in neutrophils, such as MMP‐9 and ARG‐1, have been shown to promote tumor growth." (PMID 38553949, 2024). "Hence, we correlated the expression level of the tumor-upregulated gene signature, comprising HAS2, MMP9, CXCL8, CXCL11, IL1B, and IL6, with the ratio of infiltrating M1 macrophages." (PMID 38329386, 2024). "Through cell function and mechanism studies, it was found that compounds 7a and 7j downregulated the expression of Bcl-2, Caspase9, and MMP9 proteins, upregulated the expression of Cleaved-Caspase3 and Cleaved-PARP proteins, inhibited tumor cell proliferation and migration, promoted cell apoptosis." (PMID 38649732, 2024). "Notably, MMP-9 and MMP-2 are key contributors, as they proteolytically cleave and activate latent transforming growth factor-beta (TGF-β), thereby promoting tumor angiogenesis." (PMID 38672182, 2024). "Notably, we observed an influence of TIMP1, demonstrating a positive correlation with MMP8, MMP9, and MMP10 in tumor samples." (PMID 38474106, 2024). "Specific MMPs, including MMP2, MMP9, MMP11, MMP14, MMP15, MMP25, and MMP28, were increased in this region, indicating their distinct roles in the tumor microenvironment and confirming the importance of understanding the effects of cysteamine on specific MMPs in GBM cancer models." (PMID 38893149, 2024). "DOX and CpG release via MMP-9 enzyme in TME could increase tumor-specific antigen (TSA) releasing and recruitment of CD8 + and CD4 + T cells to both tumor environments and spleen, repressing tumor development, and improving animal survival." (PMID 38951806, 2024). "Furthermore, in CTC, MMP‐9 expression was also significantly higher than that in primary tumours, indicating that HCC cells with elevated MMP‐9 levels demonstrate an enhanced ability to invade the blood circulation system." (PMID 38506084, 2024). "The extracellular vesicles produced by this cell line can polarize neutrophils towards the pro-tumour (N2) subtype, which increases the migratory potential, the release of NETs, extracellular DNA, IL-8, ARG-1 expression, MMP9 activity, and the overall increase in viability of TNBC cells." (PMID 38398138, 2024). "MMP-9 can break down ECM, releasing a variety of angiogenic factors, including VEGF and fibroblast growth factor 2 (FGF2), that act upon nearby endothelial cells to promote tumor angiogenesis." (PMID 37158964, 2023). "MMP-9 had a statistically significant higher level in PTC tumor tissues with metastasis than without metastasis (p < 0.05)." (PMID 37175113, 2023). "In addition, crocin can inhibit tumor invasion and metastasis through down-regulation of matrix metalloproteinase 2 and 9 (MMP2 and MMP9), N-cadherin, and beta-catenin expression and cell cycle suppression at G1, G0/G1, S, and G2/M phases." (PMID 38201944, 2023). "Furthermore, when we analyzed the transcriptomic data from TNBC subtype BRCA biopsies deposited in TCGA, we found that tumor expression of Foxp3 positively correlated with the expression of MMP-2 and MMP-9." (PMID 37766222, 2023).
tumor (continued). "AXL tyrosine kinase promotes tumor progression through serine/threonine protein kinase (AKT)/GSK-3β/β-catenin signaling, β-catenin nuclear-translocation-induced snail family transcriptional repressor 1 (SNAIL) transcription, and activation of MMP-2 and MMP-9." (PMID 37046676, 2023). "Furthermore, BBR suppresses migration and invasion of tumor cells via the IL-6/JAK2/STAT3 signaling pathway and inhibiting MMP-9 protein levels." (PMID 37371856, 2023). "In addition, matrix metalloproteinase 2 (MMP2) and MMP9 are secreted into the ECM and degrade mesenchymal components; their expression levels correlate with aggressive tumor phenotypes in many cancers 43-45." (PMID 37771777, 2023). "On the one hand, N1-type neutrophils have high immune activity and promote the activation of CD8+ T cells to induce tumor cell killing; on the other hand, N2-type neutrophils can release matrix metalloproteinase 9 (MMP 9) to promote angiogenesis and spread of tumor cells." (PMID 38124739, 2023). "In contrast, the pro-tumor TANs have higher levels of Arginase 1 (Arg1), CD206, Ym1, IL-6, CCL17, CXCR4, neutrophil elastase (NE), matrix metalloproteinase 9 (MMP9), vascular endothelial growth factor (VEGF), and the neuropeptide prokineticin 2 (PROK2, also known as Bv8)." (PMID 37496019, 2023). "In the presented study, the expression of MMP2, MMP9 and TIMP1 genes was assessed in the blood of NSCLC patients at three time points, before the tumor removal surgery, 100 days after surgery and one year after surgery, and in the tumor tissue." (PMID 37509417, 2023). "Primary tumor-secreted factors, such as VEGF, then induce MMP-9 in lung ECs and macrophages." (PMID 37350937, 2023). "Altogether, our analysis provided lines of evidence to support the hypothesis that macrophages may express MMP9 and CTSK in order to help tumor cell growth and break through the seminiferous tubules." (PMID 38123589, 2023). "In addition, metalloproteinases MMP3, MMP9, MMP10 and MMP13, known to promote tumor growth, were upregulated by CX3CL1 mediated activation of CX3CR1." (PMID 37771579, 2023). "Furthermore, TAMs produce proteases such as urokinase-type plasminogen, plasmin, and MMPs (for example, MMP-1, MMP-2, MMP-3, MMP-9, and MMP-12) that can promote tumor angiogenesis and can directly remodel ECM." (PMID 36908706, 2023). "Both in vitro and in vivo studies confirmed that EVs rich in these miRs inhibit cell proliferation and migration but also induce apoptosis by downregulation of several angiogenesis-related factors (such as VEGFA, MMP-9 and ANGPT) and inhibit micro-vascular formation in OSCC tumours." (PMID 37242569, 2023). "MMP-9 activates VEGF and fibroblast growth factor-2 (FGF-2), which promotes vascular endothelial cell proliferation, pro-angiogenesis and signaling, providing nutrition to tumors and promoting tumor metastasis." (PMID 36855112, 2023). "Heparanase helps drive SEVs secretion and alters exosome composition (increase in matrix metalloproteinase-9 (MMP-9), VEGF, hepatic growth factor 2 (HGF2), and receptor activator of nuclear factor κ-B ligand (RANKL)) that impact both tumor and host cell behavior." (PMID 37108371, 2023). "In addition, an IHC assay with the transplanted tumours indicated high expression of p-SMAD3, MMP2, MMP9 and MMP14 in the control group." (PMID 37689715, 2023). "In addition, by secreting vascular endothelial growth factor (VEGF), prokineticin 2 (Prok2) and matrix metalloproteinase 9 (MMP9) MDSCs foster tissue remodelling and angiogenesis thus sustaining tumour growth." (PMID 36691794, 2023). "Furthermore, in the facilitation of metastasis, TIE2-expressing PvTAMs have been demonstrated to release matrix metalloproteinase 9 (MMP9), which can promote the invasion of tumor cells and TIE2 can facilitate the transendothelial migration event." (PMID 37199172, 2023).
tumor (continued). "In addition, we measured the expression of MMP2 and MMP9 and found that the expression levels of both MMP2 and MMP9 were decreased in circUCP2-knockdown tumor tissues." (PMID 37744277, 2023). "Our data found that DOKD may suppress tumor development via adjusted metastasis and invasive through p-SRc/HIF-1α/Erk1/2/Snail and MMP9 signaling pathways." (PMID 37239383, 2023). "Moreover, a variety of MMPs (MMP1, MMP2, MMP9) as well as CAF-secreted ECM components such as periostin and tenascin-C, play a crucial role in tumor development." (PMID 36980187, 2023). "The results of the present study showed that after CRC liver metastasis, the SHP-2MAC-KO + planted tumor group obtained significantly higher levels of p-Tie2, p-PI3K, p-Akt, p-mTOR, VEGF, COX-2, MMP2, MMP9 in the liver tissue than the SHP-2WT + planted tumor group." (PMID 37304233, 2023). "In addition, periostin drives the epithelial–mesenchymal transition (EMT) via induction of matrix metalloproteinase 9 (MMP‐9), MMP‐10, and MMP‐13 expression, resulting in local tumor spread via extracellular matrix degradation." (PMID 36691359, 2023). "Furthermore, the immunofluorescence assay of tumor tissues was measured to demonstrate the expression of the M2-phenotype marker (CD206, VEGF, MMP-9), and M1-phenotype marker (CD86)." (PMID 36759928, 2023). "ATF3 is also known as an activator of the tumor invasive potential by up-regulating the expression of the matrix metalloproteinase (MMP) family members (i.e., MMP-1, MMP2, MMP-9 and MMP-13), whose mRNA and protein abundance are correlated with BC invasion and metastasis." (PMID 37447165, 2023). "SPP1+ macrophages from tumor tissues showed high expression of MMP9, MMP12, MMP14, and MMP19, which could contribute to the degradation of the basement membrane for the invasion of tumor cells." (PMID 38347955, 2023). "Identical results were obtained for tumor tissue patients with adjuvant chemotherapy (TIMP1 (p = 0.3108); MMP2 (p = 0.6402); MMP9 (p = 0.5738)) and without adjuvant chemotherapy (TIMP1 (p = 0.2654); MMP2 (p = 0.69); MMP9 (p = 0.5649))." (PMID 37509417, 2023). "MMP-9 was mostly absent in tumor cells and mostly present in inflammatory cells, necrotic areas, and MVP." (PMID 37190125, 2023). "Curcumin enhanced the anti-CRC activity of capecitabine in HCT116 tumor xenografts in male athymic nu/nu mice through the induction of apoptosis and inhibition of angiogenesis, invasion, and metastatic factors, such as VEGF, ICAM-1, and MMP-9, and CXCR4." (PMID 36765950, 2023). "As MMP-9 has been found to be overexpressed in tumors, DDSs may be also accompanied within the MMP-9 cleavable linker to achieve tumor EMC-specific drug release." (PMID 37049234, 2023). "Furthermore, MDSCs influence tumor progression and metastasis by forming a pre-metastatic niche, promoting angiogenesis and tumor cell invasion by producing higher levels of FGF, VEGF, VEGF analog Bv8, and MMP-9." (PMID 37894474, 2023). "Based on these considerations, we sought to determine whether the MMP-9 (an endopeptidase involved in ECM degradation, thus having a role in tumour invasion) level of serum-derived sEVs can provide information about patient survival." (PMID 36765669, 2023). "In addition to their individual diverse functions, LCN2, MMP9 and LOXL2 are all secreted proteins and are involved in reshaping the ECM, contributing to the progression, invasion, and migration of tumours." (PMID 37753805, 2023). "Moreover, both chalcones inhibit tumor cell invasion and migration, accompanied by downregulation of MMP-2 and MMP-9." (PMID 37373500, 2023). "Representative IHC images showed higher expression of MMP12 and MMP9 in the tumor stroma of LUAD compared with adjacent noncancerous lung tissues and tissues from patients taking atorvastatin." (PMID 37978381, 2023).
tumor (continued). "Another research proves that only active patterns of MMP-9, rather than the total levels of MMP-9, have significant associations with lymph node metastasis, extrathyroidal invasion, and degree of tumor infiltration." (PMID 37175113, 2023). "It was also of note that our finding indicated that ECs from the non-tumor zone from prostatectomy specimens (C3) showed higher expressions of MMP-9 -11, and TIMP-3 than ECs from the zone without future cancer development from biopsy (C1)." (PMID 37108185, 2023). "In addition, matrix metalloproteinase 9 (MMP9) plays an essential role in extracellular matrix remodeling, which is critical in cell migration, invasion, and angiogenesis, promoting tumor progression." (PMID 37239383, 2023). "MMP-9 had a statistically significant higher level in PTC tumor tissues with metastasis than without metastasis (p = 0.000)." (PMID 37175113, 2023). "Therefore, the invasive ability of tumor cells should be proportional to the expression of MMP-2 and MMP-9." (PMID 36785788, 2023). "To understand the molecular mechanism through which integrin β3 regulated cell invasion, we performed Western blot to detect the protein levels of the tumor cell invasiveness inducers, MMP2 and MMP9 (Supplementary Fig5A, 5C), in ITGB3 interfered cells and control cells." (PMID 36944577, 2023). "Additionally, IL-19 involved the role of MMP2, IL-6, MMP9, IL-1β, CXCR4, fibronectin, and TGF- β for tumor development." (PMID 37675062, 2023). "Indeed, the overexpression of MMP-9 seen in PDAC plays a critical and complex role in immune suppression, tumor progression, invasion, and metastasis." (PMID 36874130, 2023). "MMP-9 had a statistically significant higher level in tumor tissues than non-tumor tissues in PTC (p = 0.01)." (PMID 37175113, 2023). "Correspondingly, inhibition of MMP-9 by monoclonal antibody and TIMP-1 decreased MDSCs, which may inhibit tumor’s evasion of the immune response." (PMID 37766868, 2023). "Hematoxylin and eosin (H&E) stain, both the PDSOs and matched patients’ tumor showed atypical spindle cell proliferation in LMS, LS, and DFSP patients.Both PDSOs and patients’ tumor displayed similar expression of markers, including Ki67, CD34, PARP1, VIM, and MMP9." (PMID 37686615, 2023). "Versican can promote tumor cell invasion and metastasis by activating NF-κB signaling and upregulating the hyaluronic acid receptor CD44, receptor for HA mediated motility(RHAMM), and matrix metalloproteinase 9 (MMP9)." (PMID 37259101, 2023). "According to our results, piperine reduced cell migration by regulating MMP2 and MMP9 and their action on their respective antagonists, as TIMP1 and TIMP2 inactivate metalloproteinases and prevent their action, triggering a reduction in tumor cell migration." (PMID 36678600, 2023). "Surprisingly, MMP-9 activated tumor-infiltrating macrophages into a tumor-inhibiting phenotype, inhibited tumor growth and angiogenesis, indicating MMP-9’s potential in regulating the innate immune response into anti-tumor action." (PMID 37766868, 2023). "However, MMP2, MMP9, and other proteolytic enzymes in local inflammations from PDT can cooperate in tissue damage by facilitating a reduction in tumor volume." (PMID 37239013, 2023). "Furthermore, compared with the SHP-2WT + planted tumor group, the SHP-2MAC-KO + planted tumor group exhibited a significant increase in p-Tie2, p-PI3K, p-Akt, p-mTOR, VEGF, COX-2, MMP2, and MMP9 in the liver tissue." (PMID 37304233, 2023). "MMP-9 had a statistically significant higher level in tumor tissues than non-tumor tissues in both non-metastatic PTC (p < 0.01) and metastatic PTC (p < 0.001)." (PMID 37175113, 2023). "In addition, neutrophils can also secrete bioactive substances that promote tumor progression, including VEGF, MMP9, Oncostatin M (OSM), IL-1β, ​​TNF-a, IL-8, CXCL3, ROS." (PMID 37644468, 2023).